GCM1 (GCM transcription factor 1)
Description:
Transcription factor involved in the control of expression of placental growth factor (PGF) and other placenta-specific genes. Binds to the trophoblast-specific element 2 (TSE2) of the aromatase gene enhancer. Binds to the SYDE1 promoter. Has a central role in mediating the differentiation of trophoblast cells along both the villous and extravillous pathways in placental development.
Synonyms: hGCMa; GCMA
Tractability: PROTAC: UniProt records ubiquitination sites on it.
Gene: Protein-coding gene on chromosome 6 (53,126,961 to 53,148,841, reverse strand). Ensembl gene ENSG00000137270.
Subcellular location: Nucleus
Gene Ontology:
Molecular function: DNA-binding transcription activator activity, RNA polymerase II-specific; DNA-binding transcription factor activity; DNA-binding transcription factor activity, RNA polymerase II-specific; histone deacetylase binding; protein binding; RNA polymerase II cis-regulatory region sequence-specific DNA binding; sequence-specific double-stranded DNA binding; DNA binding; zinc ion binding
Biological process: positive regulation of DNA-templated transcription; positive regulation of transcription by RNA polymerase II; regulation of cell differentiation involved in embryonic placenta development; regulation of DNA-templated transcription; transcription by RNA polymerase II; anatomical structure morphogenesis; cell differentiation involved in embryonic placenta development; gliogenesis; regulation of transcription by RNA polymerase II
Cellular component: nucleus; transcription regulator complex; chromatin
Genetic constraint (gnomAD): Loss-of-function variants: 2 observed, 15.59 expected, observed/expected ratio (o/e) 0.13, 90% interval 0.051 to 0.4. The upper end of that interval is the gene's LOEUF score, 0.4, which puts it in group 1 of 6, group 1 being the genes least tolerant of losing a copy. Missense variants: 322 observed, 426.52 expected, observed/expected ratio (o/e) 0.75, 90% interval 0.69 to 0.83. Synonymous variants: 144 observed, 160.84 expected, observed/expected ratio (o/e) 0.9, 90% interval 0.78 to 1.03.
Homologues: Orthologues: chimpanzee GCM1 (99% identical), macaque GCM1 (98% identical), dog GCM1 (82% identical), rabbit GCM1 (81% identical), guinea pig GCM1 (76% identical), rat Gcm1 (74% identical), pig GCM1 (74% identical), mouse Gcm1 (74% identical), tropical clawed frog gcm1 (42% identical), Drosophila melanogaster gcm (29% identical), Drosophila melanogaster gcm2 (28% identical). Paralogues in human: GCM2 (35% identical).
Diseases named in the same sentence as GCM1 in open-access papers:
GCM1 is named in the same sentence as 32 diseases in open-access papers, as found by Europe PMC text mining. Sharing a sentence is not in itself a finding about the gene and the disease. The quoted sentences say what the papers report.
preeclampsia (16 papers, 2008 to 2025). Preeclampsia is a hypertensive disorder of pregnancy that is characterized by new-onset hypertension with proteinuria presenting after 20 weeks of gestation, and depending on mild or severe forms may initially present with severe headache, visual disturbances, and hyperreflexia. "Inadequate GCM1 expression is linked to preeclampsia (PE), a clinical condition caused by poor placentation." (PMID 35338152, 2022). "Reduced placental GCM1 expression causes defective syncytiotrophoblast differentiation and maternal and placental preeclampsia-like phenotypes in mice and is inversely associated with placental vascularization in humans." (PMID 34576036, 2021). "Aberrant syncytialization has been implicated in preeclampsia, and several reports have indicated that the master players in syncytialization, including GCM1 and the syncytins, are also downregulated in preeclampsia." (PMID 32628362, 2020). "It was found that in this subform of preeclampsia there is a decreased placental expression of GCM1 and ESRRG, genes encoding transcription factors that regulate trophoblastic LGALS13 expression." (PMID 25191322, 2014). "In our study, Gcm-1 expression in human placentae was reduced in preeclampsia patients compared to healthy controls and negatively correlated with inflammasome marker cleaved IL-1β." (PMID 34576036, 2021). "Reduced placental expression of GCM1 and abnormal syncytiotrophoblast structure are features of hypertensive disorder of pregnancy – preeclampsia." (PMID 23300953, 2013). "Numerous known key modulators of preeclampsia (such as Endoglin, Syncytin, human chorionic gonadotrophin -hCG-, and Glial Cell Missing Homolog -GCM1-) were modified in these transformed choriocarcinoma cells." (PMID 19079545, 2008). "Furthermore, blood pressure, a clinical parameter used to identify the onset of preeclampsia, was negatively correlated with GCM1 and positively correlated with IL-1β expression." (PMID 34576036, 2021). "Additionally, reduced GCM1 expression has been linked with increased tissue inhibitor of metalloproteinase-4 (TIMP4) expression in preeclampsia, indicating a mechanistic link between GCM1, placental tissue-remodeling and placental vascularization." (PMID 28383551, 2017). "It is important that the impairment of villous trophoblast syncytialization characterized by the decreased trophoblastic expression of GCM1 and syncytin-1, a fusogenic protein regulated by GCM1, has been observed in preeclampsia, an obstetrical syndrome originating from impaired early placentation." (PMID 25191322, 2014). "Interestingly, levels of GCM-1 are downregulated in the placentas of women suffering from severe preeclampsia, a pregnancy complication characterized by impaired villous structure and placental development." (PMID 24711815, 2014). "GCM1 has been found to be decreased in placenta from pregnancies complicated by preeclampsia." (PMID 20967267, 2010). "Consequently, we identify mitochondrial creatine kinase 1 (CKMT1) as a key GCM1 target crucial for syncytiotrophoblast differentiation and reveal decreased CKMT1 expression in preeclampsia." (PMID 35338152, 2022). "Although fetal growth in Gcm1+/− conceptuses is not affected, wild-type females carrying Gcm1+/− conceptuses develop late gestational hypertension similar to what is seen in pre-eclampsia patients." (PMID 30319550, 2018). "GCM-1 may be regulated by the transcription factor peroxisome proliferator-activated receptor-gamma (PPAR-γ); in mice, PPAR-γ promotes labyrinthine trophoblast differentiation via Gcm-1, and, as we previously demonstrated, PPAR-γ activation ameliorates disease features in rat model of preeclampsia." (PMID 24711815, 2014).
placental cancer (2 papers, 2024 to 2025). "New roles for GCM1 in placental development and placental cancer may have yet to be discovered." (PMID 40280139, 2025). "New roles for GCM1 in placental development and placental cancer may as yet be discovered." (PMID 39314437, 2024).
seminoma (2 papers, 2017 to 2023). A radiosensitive malignant germ cell tumor found in the testis (especially undescended), and extragonadal sites (anterior mediastinum and pineal gland). "In the panel of randomly selected seminomas and non-seminoma GCTs, we detected similarly low levels of GCM1 expression (median 0.3350% POLR2A and 0.7493% POLR2A, respectively) that was not increased over the tumor-matched controls and non-GCT testes." (PMID 28302141, 2017). "Neither the transcription factor GCM1 nor the increased copy number of ERVWE1 were sufficient for this aberrant expression of syncytin-1 in seminomas." (PMID 28302141, 2017). "We concluded that high levels of ERVWE1 expression in seminomas were not mediated by the GCM1 transcription factor." (PMID 28302141, 2017). "The interaction of syncytin-1 and its receptor SLC1A4/SLC1A5, and the transcriptional factor glial cells missing transcription factor 1 (GCM1) are all able to influence most tumorigenesis, nevertheless, the interaction has not been found in TGCT or seminomas." (PMID 37326913, 2023).
spina bifida (2 papers, 2017 to 2021). A congenital neural tube defect in which vertebrae are not fully formed. "Apart from the 3 mutants with only spina bifida (Fgfr1, Shp2, and Gcm1) which have 2 neural tubes with one notochord, 2 other mutants with spinal defect but no spina bifida share the same predicament." (PMID 28286691, 2017). "Ectopic expression of Gcm1 leads to spina bifida in transgenic mice and frequently with a lipoma at the spinal cord, which shared a characteristic with the human spinal dysraphias and suggests human low-axial spina bifida may be related to Gcm1 ectopic expression." (PMID 33664222, 2021).
ZIKV infection (2 papers, 2019 to 2023). "We observed a down-regulated expression of GCM1, OVOL1, ERVW-1, and ERVFRD-1 in hTSCs following ZIKV infection." (PMID 37684223, 2023).
autism (1 paper, 2020). Persistent deficits in social interaction and communication and interaction as well as a markedly restricted repertoire of activity and interest as well as repetitive patterns of behavior. "Additionally, GCM1 showed highly significant enrichment for known autism susceptibility markers (P = 5.49E-07; Fisher’s exact test), and the expression levels of genes in this module were significantly higher during early brain development." (PMID 32576137, 2020).
breast carcinoma (1 paper, 2018). "Recently, it has been postulated that infection by an exogenous virus can trans˗activate ENV ectopically by increasing the expression of GCM1 and promoting syncytia formation in breast cancer and endometrial carcinoma." (PMID 29439661, 2018).
cardiomyopathy (1 paper, 2024). A disease of the heart muscle or myocardium proper. "GCM1 is a protein-coding gene, which is associated with cardiomyopathy and pre-eclampsia, described as a placenta-specific gene, also influenced by a high fat diet during gestation in mice, but with no known function in liver diseases." (PMID 39142818, 2024).
colon cancer (1 paper, 2021). "More recently, it has been reported that the expression of syncytin-1, GCM1, and ASCT-2 is associated with a wide variety of cancers, including colon cancer." (PMID 34676163, 2021).
endometriosis (1 paper, 2016). The growth of functional endometrial tissue in anatomic sites outside the uterine body. "This indicates that the study of GCM1 and GCM2 in endometriosis should be carried out using highly sensitive methods and possibly during the development of the disease to catch the transient presence of their transcripts." (PMID 27886257, 2016).
folate (1 paper, 2021). "Remarkably, Nanog, which binds with Gcm1 at TBE motifs in the first 1 kb of the Gcm1 promoter, can positively regulate Gcm1 transcription under folate deficiency." (PMID 33664222, 2021).
folate deficiency (1 paper, 2021). A nutritional condition produced by a deficiency of FOLIC ACID in the diet. "To understand how folate level affect Gcm1 expression, we performed the DNA methylation of Gcm1 with folate deficiency, considering that folate serves as a source of epigenetic modifications in S-adenosylmethionine (SAM)-mediated one-carbon transfer reactions." (PMID 33664222, 2021). "Overall these data indicated that the Gcm1/β-catenin/TCF4 tri-complex bound to Wnt target genes in folate deficiency, in which Gcm1 had specifically linked to Wnt target promoters." (PMID 33664222, 2021). "Taken together, these results demonstrated that abnormal expression of GCM1 modulated Wnt/β-catenin signaling during the development of mammalian nervous system in folate deficiency." (PMID 33664222, 2021). "As Nanog binding motifs harboring TBEs are enriched within a 1 kilobase (kb) region of the Gcm1 promoter, the impact of Nanog on Gcm1 gene expression in folate deficiency was investigated." (PMID 33664222, 2021). "Overall, these results demonstrated that Nanog was a critical player in the control of Gcm1 expression with folate deficiency." (PMID 33664222, 2021). "Considering that Gcm1 regulates cell fusion associated with Wnt/β-catenin signaling in syncytiotrophoblast cells, we therefore investigated to know whether increased Gcm1 expression regulates Wnt/β-catenin in folate deficiency." (PMID 33664222, 2021). "Notably, Gcm1 transcription was ranked the highest among all selected genes under folate deficiency (fold change > 2, P < 0.05)." (PMID 33664222, 2021). "However, no different epigenetic regulation in the promoter region of Gcm1 was found with folate deficiency." (PMID 33664222, 2021). "To explore whether Gcm1 was involved in modulating the transcription of Wnt target genes in folate deficiency, we performed genome-wide ChIP-seq of Gcm1 in mESCs to determine its binding characteristics." (PMID 33664222, 2021). "Since it has been confirmed that TCF4 plays a pivotal role in the activation of Wnt/β-catenin pathway, we also performed Co-IP assay between Gcm1 and TCF4 in folate deficiency." (PMID 33664222, 2021). "The results showed an increase in binding between Gcm1 and TCF4 in folate deficiency." (PMID 33664222, 2021).
gestational choriocarcinoma (1 paper, 2025). Gestational choriocarcinoma is a gestational trophoblastic tumor (GTT) occurring secondary to pregnancy (ectopic or normal), miscarriage, voluntary termination of pregnancy (VTP) or a hydatidiform mole. "Interestingly, despite its growth-restricting properties in culture, GCM1 is not a known tumor suppressor in gestational choriocarcinoma (GC)." (PMID 40280139, 2025).
placental disease (1 paper, 2017). "Thus, the current study does not only corroborate the in vivo relevance of previous work by others and us,18, 19, 26 but in addition identifies a (patho-) physiological relevance of p45 NF-E2 and post-translational modifications of GCM1 in human trophoblast cells and placental disease." (PMID 28383551, 2017). "Likewise, it remains unknown whether other post-translational modifications of GCM1, which modulate GCM1 activity, are regulated by p45 NF-E2 and – importantly – the relevance of these findings for human trophoblast cells and placental disease in humans remains unknown." (PMID 28383551, 2017).
tumor (8 papers, 2017 to 2025). "In conclusion, ATO can promote tumor progression by inducing the formation of PGCCs via GCM1/syncytin-1-mediated cell fusion." (PMID 34676163, 2021). "Here we show that a series of transcription factors, including C/EBPβ, GCM1, and GATA1, could act as potential modulators of histone methylation in tumor cells." (PMID 29712898, 2018).
cancer (4 papers, 2013 to 2023). A tumor composed of atypical neoplastic, often pleomorphic cells that invade other tissues. "GCM1, a Glial Cells Missing 1 transcription factor, has been implicated in tumorigenesis, angiogenesis, and invasion of various cancers." (PMID 37035732, 2023). "Results showed that these significantly expressed mtio-ncRNAs mainly enriched the Cancer Gene Neighborhoods pathway, and further analysis of the Cancer Gene Neighborhoods pathway revealed that the main target genes were GCM1 and ACTG1 genes." (PMID 37035732, 2023). "Further analysis revealed that these miRNAs mainly enriched the Cancer Gene Neighborhoods pathway, with GCM1 and ACTG1 as the main target genes." (PMID 37035732, 2023). "Our study indicated that the expression of GCM1 in control cancer cells and PGCCs with daughter cells in LoVo and Hct116 cells was increased after MG132 treatment." (PMID 34676163, 2021). "Using a loss of function approach in two culture models, the chorio-carcinoma cell line BeWo and first trimester placental explants, we were able to demonstrate that DREAM negatively regulates transcription of GCM1 and thus restricts villous trophoblast turnover." (PMID 23300953, 2013). "WB assays also confirmed that the expression of cell fusion-related proteins, including p-ERK1/2(mouse), p-ERK1/2(rabbit), ERK1/2, P38 MAPK, β-catenin, GCM1, syncytin-1, and ASCT-2, increased compared to that in control cancer cells, and the differences were statistically significant." (PMID 34676163, 2021).
infection (3 papers, 2014 to 2018). The state of being infected such as from the introduction of a foreign agent such as serum, vaccine, antigenic substance or organism. "Conversely, the overexpression of VASH2 by the AdVASH2 infection augmented the fusion of BeWo cells without any changes in the expression of Gcm-1, Syn-1, and Syn-2." (PMID 25184477, 2014). "Importantly, the AdVASH2 infection did not alter the expression of Gcm-1, Syn-1 and Syn-2 in BeWo cells." (PMID 25184477, 2014).
GCM1 also shares sentences with these, for which no sentence is quoted: gastric cancer (4 papers); colorectal cancer (2); hydatidiform mole (2); acute kidney injury (1); basal cell carcinoma (1); choriocarcinoma (1); endometrial carcinoma (1); hypoparathyroidism (1); Influenza infection (1); lipoma (1); liver diseases (1); parathyroid adenomas (1); placental insufficiency (1); schizophrenia (1); Thrombocytopenia (1).